ICAM1 (intercellular adhesion molecule 1)
Diseases named in the same sentence as ICAM1 in open-access papers (continued):
Sharing a sentence is not in itself a finding about the gene and the disease.
atherosclerosis (continued). "IgG antibodies against herpesviruses, carotid intima-media thickness (cIMT), endothelial function through flow-mediated dilatation (FMD) of the brachial artery, and blood atherosclerosis biomarkers (hsCRP, TNF-α, IL-6, MCP-1, MDA, sCD14, sCD163, VCAM-1, ICAM-1, D-dimer, and PAI-1) were measured." (PMID 23717597, 2013). "Finally, previous studies have suggested that upregulation of cell adhesion molecules expression, such as ICAM -1 and VCAM-1, play an important role in atherosclerosis development." (PMID 23469284, 2013). "The inflammation process in large vessels involves the up-regulation of vascular adhesion molecules such as endothelial cell selectin (E-selectin), intercellular cell adhesion molecule-1 (ICAM-1) and vascular cell adhesion molecule-1 (VCAM-1) which are also known as the markers of atherosclerosis." (PMID 24129228, 2013). "The decreases of VCAM-1 and ICAM-1 of the present study suggested that moderate consumption of TFL and TCL may have a protective effect on the initial phases of the atherosclerosis process." (PMID 22919307, 2012). "In 2001, Myron I. Cybulsky demonstrated that VCAM-1, but not ICAM-1, plays a dominant role in the initiation of atherosclerosis." (PMID 22900050, 2012). "In early part of atherosclerosis, nuclear factor-kappa B (NF-κB) induces the expression of cellular adhesion molecules such as vascular cell adhesion molecule-1 (VCAM-1), intracellular adhesion molecule-1 (ICAM-1) and E-selectin." (PMID 21496279, 2011). "The ICAM-1 and VCAM-1 are important factors in the development of atherosclerosis and may play an important role in promoting the local inflammation within the atherosclerotic plaque." (PMID 21214952, 2011). "Data accumulated from mouse studies and in vitro studies of human arteries support the notion that soluble intercellular adhesion molecule-1 (sICAM-1) and monocyte chemoattractant protein-1 (MCP-1) play important roles in the inflammation process involved in atherosclerosis." (PMID 17963506, 2007). "Furthermore, IS participates in the pathophysiology of atherosclerosis by upregulating the expression of monocyte chemotactic protein 1 (MCP1), intercellular adhesion molecule-1 (ICAM-1), and E-selectin, inducing leukocyte–endothelial interactions and promoting inflammation." (PMID 40869261, 2025). "To establish the presence of ICAM-1 in atherosclerotic lesions in our experimental animal model, we conducted immunofluorescence analysis (IFA) to examine the expression of ICAM-1 on luminal endothelium in the aortas of 22-week-old ApoE−/− mice fed with HFD to recapitulate atherosclerosis." (PMID 40630903, 2025). "Furthermore, the fact that BSA-nanocarrier-coated MSCs achieved only partial localization to sites of atherosclerosis demonstrates that upregulation of ICAM-1 levels alone is not sufficient to recruit unmodified MSCs into the aorta." (PMID 40630903, 2025). "VCAM-1 and ICAM-1 (Intercellular Adhesion Molecule 1) are upregulated in atherosclerosis lesions, but Cybulsky and collaborators demonstrated in mice models that VCAM-1 was involved in the initial stage of atherosclerosis while ICAM-1 was involved in lesion progression." (PMID 39273200, 2024). "Overexpression of COX-2 enhances the expression of intercellular adhesion molecule-1 (ICAM-1) and vascular cell adhesion molecule-1 (VCAM-1), facilitating the recruitment of inflammatory cells to the vascular wall, further accelerating the development of atherosclerosis." (PMID 39517211, 2024). "Additionally, various studies have shown that adhesion molecules that mediate the recruitment of leukocytes at sites of inflammation, such as endothelial-leukocyte adhesion molecule-1 (E-selectin) and intercellular adhesion molecule-1 (ICAM-1), are increased in individuals with atherosclerosis." (PMID 36983851, 2023).
atherosclerosis (continued). "Prior studies have reported that some components of the MedDiet such as nuts may downregulate inflammatory markers related to atherosclerosis, such as serum C-reactive protein (CRP), interleukin 6 (IL-6), cell adhesion molecule-1 (CAM-1), and intercellular adhesion molecule-1 (ICAM-1)." (PMID 35192097, 2023). "In atherosclerosis model (LPS-stimulated Bovine aortic endothelial cells/plasmid transfected endothelial cells/HUVECS/VSMC), SFN reduced the expression of intracellular adhesion molecule (ICAM-1), VCAM-1 (vascular cell adhesion molecule-1), E-selectin, and MCP-1 (monocyte chemotactic protein-1)." (PMID 35163897, 2022). "Moreover, ICAM-1 and Ccl2 mRNA expression was elevated in the HFCD-induced atherosclerosis CON group compared with the NOM group, while the mRNA expression of those in the HFCD-induced atherosclerosis with GPE treated group decreased significantly (p < 0.05)." (PMID 36145277, 2022). "Atherosclerosis starts with EC activation mainly due to lipid mediators such as oxidized low density lipoprotein (ox-LDL), which upregulates the expression of endothelial adhesion receptors such as intercellular adhesion molecule-1 (ICAM-1) and vascular adhesion molecule-1 (VCAM-1)." (PMID 33804952, 2021). "Given the vital role of G2A in the pathogenesis of inflammation and immune related diseases, and our previous studies that G2A regulates the LPC-induced expression of ICAM-1 and VCAM-1, we hypothesized that G2A may also be involved in the development of atherosclerosis." (PMID 34346841, 2021). "In addition to ICAM-1 and VCAM-1, CXC chemokine ligands (CXCL) have also been identified as key adhesion molecules in adhesion, migration, and recruitment of monocytes during the pathogenesis of atherosclerosis." (PMID 34388961, 2021). "In addition, it has been proposed that ICAM-1 may be predictive of cardiovascular events in adults, and VCAM-1 may be a prognostic factor in patients with atherosclerosis." (PMID 32433661, 2020). "Besides, an olive extract rich in secoiridoids has shown its capacity to weaken initial steps of atherosclerosis due to significant reduction of endothelial dysfunction biomarkers such as E-selectin, VCAM-1, MCP-1, ICAM-1 and F4/80 in ApoE−/− mice, an atherosclerosis-prone mouse model." (PMID 33322700, 2020). "Cellular adhesion molecules (CAMs), such as intercellular adhesion molecule 1 (ICAM-1) and vascular cell adhesion molecule 1 (VCAM-1), contribute to the recruitment and migration of circulating monocytes into the vessel wall, leading to a vascular inflammatory response in atherosclerosis." (PMID 31623159, 2019). "The endothelial inflammatory response includes the expression of cell adhesion molecules such as intercellular adhesion molecule-1 (ICAM-1) that allow circulating neutrophils to adhere to sites of endothelial injury, which is involved in the pathogenesis and development of atherosclerosis." (PMID 30728750, 2019). "In the development of atherosclerosis, adhesion proteins induce the recruitment of monocytes, so we evaluated the effect of nicotine and GTPCH1 on the expression of adhesion proteins such as intracellular adhesion molecule 1 (ICAM1) and vascular cell adhesion molecule 1 (VCAM1)." (PMID 30091833, 2018). "Moreover, intercellular cell adhesion molecule-1(ICAM-1), chemoattractant protein-1(MCP-1), and macrophage migration inhibitory factor (MIF), which regulate the adhesion of monocytes, are dysregulated in hyperglycemia-induced atherosclerosis in animal models." (PMID 28883907, 2017). "This was associated with decreased expression of the adhesion molecule, ICAM‐1, in both PVAT and aorta, which in concert with changes in chemokine expression may provide a mechanism for decreased recruitment of immune cells in early atherosclerosis." (PMID 27935022, 2017).
atherosclerosis (continued). "Atherosclerosis, precursor to cardiovascular diseases, is recognised as a chronic inflammatory disease of large arteries, involving cytokines, such as IFN-γ and TNF-α, adhesion molecules, such as ICAM-1 and VCAM-1, and several plasma inflammatory markers, such as hsCRP, IL-6, and fibrinogen." (PMID 26346892, 2015). "Hence, we speculated that cilostazol inhibits the signaling of NF-kB and decreases transcription of different proteins, including ICAM-1, VCAM-1, E-selectin, TNF-α, interleukin-6 (IL-6), AGE, and ligands for RAGE in human atherosclerosis." (PMID 25666934, 2015). "Also, EAH reduced the expression of lectin-like oxidized low-density lipoprotein receptor-1 (LOX-1) (27%), intracellular adhesion molecule-1 (ICAM-1) (28%) and matrix metalloproteinase-9 (MMP-9) (19%), important molecular markers in the atherosclerosis pathway." (PMID 24891839, 2014). "In addition to cytokine and chemokines genes the “Atherosclerosis Signalling” and “Communication between Innate and Adaptive Immune cells” pathways had CD40, ICAM1, ORM1 and ORM2 as being significantly expressed within the pathways at 1 hour following LPS and Pam3CSK4 stimulation." (PMID 24842522, 2014). "Soluble adhesion molecules like intercellular adhesion molecule-1 (ICAM-1), vascular cellular adhesion molecule-1 (VCAM-1) and E-selectins are involved in the recruitment of leucocytes to sites of inflammation at the endothelium and are thus involved in the pathogenesis of atherosclerosis." (PMID 19486510, 2009). "However, there were more CD68-positive macrophages and ICAM-1-expressing cells in plaques from apoE−/−/PGC-1α−/− mice compared to those from littermate controls, implicating a potential role of macrophage PGC-1α in atherosclerosis in vivo which is in keeping with the data presented above." (PMID 23964012, 2013). "In addition, the serum TNF-α and IL-1β levels were increased in atherosclerosis rabbits, and kaempferol groups showed lower TNF-α and IL-1β levels, indicating that the down-regulation of E-sel, ICAM-1, VCAM-1 and MCP-1 might be mediated by the reducing of TNF-α and IL-1β." (PMID 23895132, 2013). "In this study, mice in the ApoEST2DKO group, with significant atherosclerosis development, showed increased VCAM1 and ICAM1 levels and a non-significant but decreasing trend in IL-4 and IL-5, consistent with previously reported results." (PMID 38674885, 2024). "The expression of ICAM-1 and VCAM-1 in cardiac muscle did not change after the onset of atherosclerosis." (PMID 30505360, 2018). "Although expression of both VCAM-1 and ICAM-1 is up-regulated in atherosclerotic lesions, VCAM1, but not ICAM1, plays a dominant role in the initiation of atherosclerosis." (PMID 25189624, 2014). "Therefore, adhesion molecule expression ICAM-1 and VCAM-1 was not upregulated in the early progression of atherosclerosis and they are less likely to contribute to cardiomyopathy because of dyslipidemia." (PMID 30505360, 2018).
endothelial dysfunction (513 papers, 2005 to 2026). In vascular diseases, endothelial dysfunction is a systemic pathological state of the endothelium (the inner lining of blood vessels) and can be broadly defined as an imbalance between vasodilating and vasoconstricting substances produced by (or acting on) the endothelium. "A post hoc analysis of clinical trial data demonstrated that tirzepatide at a dose of 15 mg significantly decreased levels of biomarkers that have been associated with endothelial dysfunction, e.g., hsCRP or ICAM-1." (PMID 41465455, 2025). "AP is also associated with endothelial dysfunction (ED), marked by elevated endothelin-1 (ET-1) and intercellular adhesion molecule-1 (ICAM-1), which disrupts vascular integrity and fosters atherogenesis." (PMID 40001895, 2025). "Frailty has been associated with endothelial dysfunction, as evidenced by the following serum markers: intercellular adhesion molecule 1 (ICAM-1), endothelin 1 (ET-1), von Willebrand factor (vWF), plasma thrombomodulin, and asymmetric dimethylarginine (ADMA)." (PMID 39335518, 2024). "We have demonstrated through in vitro experiments that IL-6 intervention in HUVECs can cause changes in the expression levels of endothelial dysfunction markers ICAM-1 and ZO-1 ——an increase in ICAM-1 expression and a decrease in ZO-1 expression." (PMID 38195507, 2024). "Elevated soluble vascular cell adhesion molecule-1 (sVCAM-1) and soluble intercellular adhesion molecule-1 (sICAM-1) levels implicated in the regulation of inflammation indicate endothelial dysfunction." (PMID 38558679, 2024). "The initial stage of atherosclerosis is due to endothelial dysfunction, which is associated with ICAM-1 and VCAM-1 overexpression." (PMID 36408439, 2022). "In contrast, serum ICAM-1 has traditionally been related to endothelial dysfunction linked with vascular damage, which is associated with OSA, and the present meta-analysis also confirmed this result." (PMID 36295659, 2022). "In said context, PCSK9 deficiency reduces endothelial dysfunction by reducing the expression of lower endothelial expression of the genes encoding, e.g., ICAM-1, CCL2, IL-6 and IL-1β." (PMID 36361853, 2022). "Elevated levels of ICAM-1 have been associated with severe endothelial dysfunction in severe COVID-19 patients." (PMID 35397534, 2022). "In summary, the results of our unsupervised clustering analysis and biomarker profiling suggest that reduced levels of protective lipids (HDL-C, ApoA-I, and LDL-C) are associated with increased endothelial dysfunction (E-selectin, ICAM-1) and worse outcomes." (PMID 34535154, 2021). "As the cMets score increased by one SD, the risk of acute inflammatory status increased 1.25-fold (95% confidence interval [CI] 1.10–1.42) and the risk of endothelial dysfunction increased 1.26-fold (95% CI 1.11–1.43) based on ICAM-1." (PMID 32433661, 2020). "On other hand, miR-126 or miR-223 that are linked to arterial thrombosis target proteins that cause endothelial dysfunction, alternation of lipid metabolism or trigger inflammation and target ICAM-1, VCAM-1, IL-6 or IL-8." (PMID 32443696, 2020). "Since HG has been causally associated with endothelial dysfunction, we explored the release of ICAM-1 under hyperglycemic conditions." (PMID 33414814, 2020). "Its circulating level can act as one marker of endothelial dysfunction which is considered as one pathogenesis of LA, indicating the pathogenic functions of ICAM1 in white matter lesions." (PMID 31396257, 2019). "This is because VCAM-1, ICAM-1, and E-Selectin are all markers of endothelial dysfunction, and have been implicated in the pathology of SCD." (PMID 29690499, 2018). "Several parameters of possible mechanisms (PRA, aldosterone, endothelial dysfunction-ICAM-1, inflammation-hsCRP, and hyperinsulinism) associated with oxidative stress were analyzed according to CKD stage in the studied group." (PMID 26885251, 2016).
endothelial dysfunction (continued). "Endothelial dysfunction was also assessed by the expression of adhesion molecules, such as ICAM-1 and VCAM-1, which have been associated with the development of CVD in diabetic patients." (PMID 23497124, 2013). "Endothelial dysfunction indicated by elevation of vWF, ICAM-1, or VCAM-1 was associated with significantly higher AF than in diabetic patients with normal levels of these parameters." (PMID 23671885, 2013). "For instance, PM2.5 exposure has been associated with elevated blood levels of two markers of endothelial dysfunction—intercellular adhesion molecule-1 (ICAM-1) and vascular cell adhesion molecule-1 (VCAM-1) —which are also shown to increase in preeclampsia." (PMID 24021707, 2013). "Possibly, disturbance of AR is fostered by the underlying inflammation caused by endothelial dysfunction due to endotoxins from bacteria, or cytokines like ICAM-1 from the immune response." (PMID 23036135, 2012). "High ICAM-1 levels are linked to increased endothelial dysfunction and cardiovascular risk." (PMID 40217801, 2025). "Endothelial dysfunction is associated with the overexpression of ICAM-1 and VCAM-1." (PMID 39457107, 2024). "Both VEGF and ICAM-1 not only play an important role in promoting tumor angiogenesis but they are also potent inducers of vascular permeability, which play a major role in the induction of endothelial dysfunction and the associated capillary leak syndrome." (PMID 39596461, 2024). "Endothelial dysfunction has been implicated in thrombotic microangiopathy in patients with severe COVID-19, with increased circulating endothelial cells and plasma levels of soluble ICAM-1, VCAM-1, and P-selectin." (PMID 37896963, 2023). "Therefore, the reduction of ICAM-1 caused by Ubq supplementation suggested that Ubq plays a crucial role in regulating endothelial dysfunction." (PMID 38151557, 2023). "Moreover, we were able to confirm the association between ICAM1 expression and endothelial dysfunction in ASCVD." (PMID 35282277, 2022). "A common hallmark of endothelial dysfunction observed in many diseases is an increased expression of adhesion molecules such as ICAM‐1, VCAM‐1, P‐, and E‐selectin that may facilitate lymphocyte adhesion to activated endothelium." (PMID 33512067, 2021). "Moreover, PCSK9 has been implicated in endothelial dysfunction by upregulating the expression of intercellular adhesion molecule-1 (ICAM-1) and vascular cell adhesion molecule-1 (VCAM-1) in endothelial cells." (PMID 34336112, 2021). "Oxidative/nitrative stress causes the upregulation of adhesive molecules, such as ICAM-1, triggers leukocyte infiltration into the infarct area, and causes endothelial dysfunction, resulting in BBB disruption and initiating vasogenic edema formation in the early phase of ischemic stroke." (PMID 33298024, 2020). "An increase of one SD in the cMets score resulted in a 1.25-fold (95% CI 1.10–1.42) increase in the risk of acute inflammatory status and a 1.26-fold (95% CI 1.11–1.43) increase in the risk of endothelial dysfunction as defined by ICAM-1, while VCAM-1 showed a meaningless trend." (PMID 32433661, 2020). "Moreover, inflammatory markers TNFα and hs-CRP together with biochemical markers of endothelial dysfunction, ICAM-1 and VCAM-1, were also stratified according to GST risk genotypes." (PMID 31275451, 2019). "Besides, a possible association between plasma levels of VCAM-1, ICAM-1, and E-Selectin, and endothelial dysfunction, exists in SCD patients." (PMID 29690499, 2018). "In addition, homocysteine levels were associated with the markers of endothelial dysfunction intercellular adhesion molecule 1 (ICAM-1) and thrombomodulin." (PMID 30037144, 2018). "Moreover, ARG1 mRNA levels are reported to be positively associated with the up-regulation of soluble intercellular adhesion molecule-1, which is a circulating biomarker for endothelial dysfunction." (PMID 24763700, 2014).